ENSG00000275693
Gene: Miscellaneous RNA gene on chromosome 10 (88,992,370 to 88,992,539, forward strand). Ensembl gene ENSG00000275693.
Gene Ontology:
Biological process: regulation of gene expression